MIURF (mitochondrial elongation factor 1 upstream open reading frame )
Synonyms: AltMIEF1; AltMiD51; MIEF1-MP
Gene: Protein-coding gene on chromosome 22 (39,504,231 to 39,504,443, forward strand). Ensembl gene ENSG00000285025.
Homologues: Orthologues: mouse Gm55359 (87% identical).